CD86 (CD86 molecule)
Diseases named in the same sentence as CD86 in open-access papers (continued):
Sharing a sentence is not in itself a finding about the gene and the disease.
Arthritis (14 papers, 2013 to 2025). Inflammation of a joint. "In favor of this, in a model of antigen-induced arthritis in mice, the blockade of CD86 reduced the severity of disease, suppressed the production of IL-17 and reduced the accumulation of effector T cells in joints." (PMID 39452128, 2024). "Expression of CD64 and CD163 on monocytes and PDL2, CD86, and HLA-DR on DC discriminate both type of arthritis." (PMID 32849606, 2020). "Costimulatory interactions of CD80 and CD86 to T cells are required for the activation of autoreactive T cells and induction of arthritis." (PMID 31582900, 2019). "In addition, compared with those of WT mice with arthritis, the proportions of F4/80+CD11b+CD86+ M1 macrophages were lower in the spleens of IGF2BP3-KO mice with arthritis." (PMID 40355406, 2025). "Exploratory mass cytometry analyses reveal three circulating cellular subsets heralding the onset of arthritis flare – CD45RO+PD1hi CD4+ and CD8+ T cells, and CD27+CD86+CD21- B cells – further characterised by single-cell sequencing." (PMID 38316770, 2024). "Consistent with this, B cell expression of the costimulatory ligands CD86 and CD80 has been shown to be essential for autoreactive T cell activation and development of joint pathology in the proteoglycan-induced arthritis model in mice." (PMID 24470500, 2014). "Notably, the expression of costimulatory factors (CD80 and CD86) and the MHC-II molecule was significantly increased on B cells from the spleen and lymph nodes in mice with established arthritis on the 35th day after immunization." (PMID 29370826, 2018).
B cell lymphoma (13 papers, 2014 to 2026). "In summary, these data suggest an increased expression of CD80/CD86 in aggressive B cell lymphomas beyond its physiological upregulation during the germinal center reaction." (PMID 38340727, 2024). "Contrary to CD86 that stimulates the proliferation of B cells and the production of IgG by B cells in B cell lymphoma, CD80 downregulates the B cell response and secretion of IgG in B cell lymphoma." (PMID 30999581, 2019). "Lymphotropic HCV strain (HCV-SB) was isolated from HCV gt2b-positive B cell lymphoma with adaptive mutations in 5’UTR and E1/E2 region and B7.2 (CD86) was identified as a lymphotropic HCV receptor." (PMID 28494029, 2017). "Mutation of Y218 to phenylalanine impairs CD86 internalization and CTLA-4-CD86 ligation-mediated Tyk2/STAT3 activity, and reduction of B cell lymphoma cell proliferation." (PMID 41486149, 2026). "DLBCL (DLBCL-NOS [not otherwise specified] and TCHRBCL [T cell/histiocyte-rich B cell lymphoma]) and FL samples showed an even higher expression of CD80 and CD86, respectively." (PMID 38340727, 2024). "Like many B-cell lymphomas, Raji cells express a wide assortment of T-cell costimulatory molecules such as CD80 and CD86." (PMID 37087494, 2023). "To further assess the anti-tumor efficacy of CTLA4-T cells against primary tumors, we developed B cell lymphoma PDX mouse models by using primary tumor tissues with high CD80 and CD86 expression." (PMID 33868277, 2021). "Murine A20 B-cell lymphoma cells expressing CD40L have been shown to upregulate CD80, CD86, ICAM-1, Fas and MHC molecules." (PMID 33666760, 2021). "In contrast, the JY and Raji B cell lymphoma cell lines, shown to be highly sensitive to CTLA4-FasL, express high levels of CD80, CD86 and CD95." (PMID 25227919, 2014). "Likewise, CD40L gene transfer in B-cell lymphoma cells from patients resulted in enhanced expression of CD80 and CD86 and generation of tumor-specific T-cell response in vitro." (PMID 33666760, 2021). "Therefore, we detected the surface expression levels of CD80 and CD86 in Pre-B acute lymphoblastic leukemia (ALL) (NALM6) and B cell lymphoma (Raji and RL) cell lines." (PMID 33868277, 2021). "A20 cells have been shown to be phenotypically similar to mature human B-cell lymphomas, expressing high levels of MHC class I and class II molecules and moderate levels of the costimulatory molecule B7-2 (CD86), and to present both exogenous and endogenous antigen." (PMID 32974162, 2020). "LOAd703 could infect and replicate in B-cell lymphoma cell lines (BC-3, Karpas422, Daudi, DG-75, U-698) and induced an overall enhanced immunogenic profile with upregulation of co-stimulatory molecules CD80, CD86, CD70, MHC molecules, death receptor Fas and adhesion molecule ICAM-1." (PMID 33666760, 2021).
acute myeloid leukemia (12 papers, 2009 to 2025). Acute myeloid leukemia (AML) is a group of neoplasms arising from precursor cells committed to the myeloid cell-line differentiation. "Previous reports have shown that HDACi can induce the expression of CD86/B7.2 costimulatory molecule in acute myeloid leukemia (AML) cells and freshly isolated AML clinical samples." (PMID 19759901, 2009). "Compound 9 showed strong anti-proliferative activities on MV-4-11 acute myeloid leukemia (AML) cell lines, induced the differentiation of AML cell lines and up-regulated the expression level of differentiation marker gene CD86 (EC50 = 470 nM)." (PMID 38276629, 2024). "For instance, AI deep learning models have successfully identified the myeloid lineage markers CD86 and CSF1R as potential therapeutic targets for acute myeloid leukemia." (PMID 40904456, 2025). "However, the interrelationships among CD86, immunotherapy, and immune infiltration in acute myeloid leukemia (AML) are unclear." (PMID 37064861, 2023). "Particularly, DNMT and HDAC inhibitors may result to an upregulation of TAAs and of co-stimulatory molecules such as CD40, CD80, CD86 and MHC classes I and II, on tumor cells, in particular in Acute Myeloid Leukemia (AML) cell lines." (PMID 39086678, 2023). "We evaluated the response of J76 PRAME TPR expressing CD2::CD28 receptors to primary acute myeloid leukemia (AML) cells that express no CD28 ligands CD80 and CD86." (PMID 29707134, 2018).
Allergy (12 papers, 2012 to 2024). An allergy is an immune response or reaction to substances that are usually not harmful. "Thus, besides investigating the allergy-associated response, levels of CD11C+CD103+ DC as well as DC expressing mutation markers, including CD80, CD86, and MHCII in MLN, were also determined using flow cytometer in the current study." (PMID 34177885, 2021). "Importantly, decreasing the expression of the co-stimulatory molecules CD80 and CD86 in DCs has been reported as a potential target for the treatment of allergic diseases." (PMID 33746954, 2021). "In an allergy model, DCs isolated from the lungs of AhR-/- mice were able to stimulate greater T cell responses to specific antigen in vitro and showed higher expression of CD86 and MHCII compared with wildtype DCs." (PMID 33339195, 2020). "As CD80 and CD86 have been found to mediate the necessary costimulatory signals to evoke Th2 polarization involved in allergy, CD80 and CD86 upregulation induced by rBla g 7 in DCs may contribute to the subsequent allergic responses." (PMID 24204099, 2013). "Notably, neither 24 nor 48 hours of co‐incubation of MA::Art v 1 VNP, Art v 1::GPI VNP, empty VNP (10 μg/mL each), or rArt v 1 protein (1 μg/mL) with bone marrow‐derived dendritic cells (BMDC) of TCR/DR1 allergy mice upregulated CD40, CD80, CD86, or MHC class II expression, when compared to medium." (PMID 30035810, 2019). "However, up-regulation of CD86 was significantly decreased on moDCs after exposure to SPPH as compared to SPP treatment, suggesting a differential role of these co-stimulatory molecules in mediating pathogenesis of human allergic diseases similar to that reported in experimental murine models." (PMID 23251688, 2012).
glioblastoma (12 papers, 2017 to 2025). The most malignant astrocytic tumor (WHO grade IV). "In the glioblastoma TME, higher expression of CD80 and CD86 was associated with shorter progression-free survival (PFS)." (PMID 40724825, 2025). "Elevated CD86 mRNA expression has recently been demonstrated as a potential prognostic biomarker for glioblastoma, and significantly enhanced CD80 and CD86 mRNA expression was detected in peripheral blood samples of CRC patients." (PMID 39456247, 2024). "For example, tumour-associated macrophages from glioblastoma have been reported to lack the costimulatory molecules CD86, CD80 and CD40, suggesting that they are not able to effectively support activation of T cells." (PMID 34676050, 2021). "Furthermore, we examined the expression of surface molecules MHCII, CD80, and CD86 in infiltrating CD45+CD103+ DCs in the Control and sh-Rab27a3 groups of glioblastoma." (PMID 39192971, 2024). "We quantified the number of CD86 (M1 marker)- and CD206 (M2 marker)-positive cells in glioblastoma (GBM) tissue samples." (PMID 39061957, 2024).
bladder cancer (11 papers, 2016 to 2024). "There were also some previous studies showing the association of CD86 with bladder cancer." (PMID 34422632, 2021). "On the other hand, Zirakzadeh found that B cells are a vector for CD86 induction and inhibit the progression of bladder cancer." (PMID 36225190, 2022). "For instance, the correlation coefficient between PRRX1 and CD86, a co-stimulatory molecule on antigen-presenting cells that had been demonstrated to act as a pivotal role in tumor immunity in pancreatic and bladder cancers, reached 0.683." (PMID 36483329, 2022). "In our study, after using bioinformatics methods to screen out CD86 via strict thresholds for each step, we focused on exploring the prognostic value of CD86 in bladder cancer." (PMID 34422632, 2021). "Additionally, the immune checkpoint proteins CD80 (B7-1) and CD86 (B7-2) are expressed on the surfaces of both tumor and immune cells, serving as significant prognostic biomarkers in various cancers, including bladder cancer and non-small cell lung carcinoma." (PMID 38904744, 2024). "we co-cultured Si-con or Si-DYM bladder cancer cell lines with M0 macrophages to detect tumor markers of CD206, CD163 and CD86 macrophages." (PMID 35769470, 2022). "In addition, PPS was found to increase the expression level of CD86 and CD40 in bladder cancer tissue of rats, and regulate the immune activity of macrophages and promoted them to M1-like macrophages." (PMID 34034714, 2021). "In addition, PPS had an inhibitory effect on the progression of bladder cancer in BBN-rat models and increased the effect on the expression levels of CD86 and CD40 in peritoneal macrophages." (PMID 34034714, 2021).
cervical carcinoma (11 papers, 2010 to 2025). A carcinoma arising from either the exocervical squamous epithelium or the endocervical glandular epithelium. "We showed that the expression of CD86 is associated with a low-risk of cervical cancer." (PMID 30020984, 2018). "Studies have examined the effect of CD86 on CIN and cervical cancer: CD80/CD86-positive dendritic cells are reported to be more abundant in the cervices of women with high-risk HPV positivity but no CIN lesions." (PMID 39302712, 2024). "In the present study, the data demonstrated that in cervical cancer, autophagy promoted the phagocytosis of macrophages, induced the expression of CD80 and CD86 and resulted in antigen presentation and immune activation, which in turn limited the tumor growth." (PMID 33390854, 2021). "In this work, we show that B lymphocytes from cervical cancer patients respond to treatment with sCD40L and IL-4 by increasing the CD80+CD86+ population, therefore potentially increasing their ability to activate T cells." (PMID 29975708, 2018). "Genes related to immune promotion, such as CD86 and CD80, have a significant negative regulatory relationship, indicating that MLK4 may affect the infiltration of immune cells in Cervical cancer by regulating the expression of immune checkpoints." (PMID 37594950, 2023). "The expression of CD80 and CD86 in the CIN group (CD80: 49.52 ± 21.74%; CD86: 46.92 ± 15.24%) was lower than that of the healthy individuals (CD80: 51.23 ± 17.16%; CD86: 49.02 ± 21.58%), and lowest in patients with cervical carcinoma (CD80: 39.59 ± 17.39%; CD86: 42.54 ± 19.51%)." (PMID 20565840, 2010). "Nonrecombinant BCG also increased the expression of these receptors on DCs, which is in contrast to the results reported by Manickam and Sivanandham showing reduced expression of CD80 but not CD86 on BCG- or PPD-stimulated DCs from patients with cervical cancer." (PMID 26339658, 2015).
endometriosis (10 papers, 2018 to 2024). The growth of functional endometrial tissue in anatomic sites outside the uterine body. "M1 macrophage therapy shifts the balance in endometriosis foci towards the predominance of CD86+ macrophages over CD206+ macrophages, resulting in an increase in macrophages with proinflammatory properties." (PMID 39253270, 2024). "Increased counts of CD86+ cells in patients with endometriosis, especially accompanied by chronic pelvic pain and persistent dysmenorrhea, indicates an extensive inflammatory process and systemic immune response." (PMID 39056769, 2024). "Another studied marker, CD86, significantly increased in the blood of patients with endometriosis, is constitutively expressed on Langerhans cells, memory B cells, macrophages and monocytes." (PMID 39056769, 2024). "Flow cytometric analysis showed that the abundance of CD68+CD86+ cells was lower than that of CD68+CD163+ in endometriosis-related peritoneal cells." (PMID 36263059, 2022). "Correlation analysis showed that in patients with endometriosis, the expression of CD86 by macrophages correlated with the levels of GLP1 and ghrelin in PF; these indicators were decreased compared with the control group." (PMID 36142272, 2022). "The percentages of CD40-positive DCs and CD86-positive DCs were declined in the mice with endometriosis, but rhIL-37 treatment increased the percentage of them." (PMID 34429116, 2021). "Monocyte-derived dendritic cells that were conditioned with serum from women with endometriosis displayed a tolerogenic phenotype, including downregulation of CD86 and HLA-DR, as well as increased IL-10 but decreased IL-12 production." (PMID 30276219, 2018). "There was a decrease in the percentage of CD86+ macrophages in the peritoneal wash solution of patients with endometriosis." (PMID 30276219, 2018). "The ratio of CD163+/CD86+ macrophages was elevated in endometriosis patients, especially in patients with advanced endometriosis (stages III-IV), who had a significantly higher ratio of CD163+/CD86+ macrophages than those with stage I-II endometriosis." (PMID 30276219, 2018). "In the blood of adolescents with endometriosis, the level of CD86+ monocytes is higher, and CD16+ is lower under the influence of the disease itself (F = 6.84, p = 0.003) under the condition of persistent dysmenorrhea (F = 15.36, p < 0.001) and chronic pelvic pain (F = 14.36, p < 0.001)." (PMID 39056769, 2024). "Therefore, we examined the distribution and abundance of the MΦ2a (CD80−/CD163+/CD206+) and MΦ2b (CD80−/CD163+/CD86+) subtypes in controls and endometriosis in the CD14+low/CD68+low and CD14+high/CD68+high subpopulations." (PMID 32572831, 2020). "Similarly, after preincubation with SB43154, the mRNA expression levels of CD163 and IL-10 were decreased while CD86 and IL-12 expression was increased in macrophages treated with serum from endometriosis patients." (PMID 30276219, 2018). "However, compared with that in control participants, the percentage of CD86+ macrophages in endometriosis patients was decreased." (PMID 30276219, 2018). "In IHC analysis, we found that CD86+ and CD206+ cells were present in the foci of endometriosis and in the endometrium." (PMID 39253270, 2024). "The peritoneal macrophages of endometriosis patients, the pMφ of patients with endometriosis with high CD206 expression, and the low expression of CD86 suggest that the pMφ of patients with endometriosis was skewed towards the M2 phenotype." (PMID 36263059, 2022). "Accordingly, PF from the patients with endometriosis was reported to downregulate the expression of the MHC class II molecules as well as CD80 and CD86 costimulatory molecules in monocytes." (PMID 34360900, 2021). "Here, rhIL-37 treatment significantly increased the proportion of CD40-, CD80-, CD86-, and MHC II-positive DCs in the blood of the mice with endometriosis, suggesting that rhIL-37 promoted DCs maturation in endometriosis." (PMID 34429116, 2021).
endometriosis (continued). "In contrast, CD86+ cells were almost absent in the peritoneal fluid of mice with endometriosis and mice after therapy but were present in healthy mice." (PMID 39253270, 2024). "In our study, we found that the serum of patients with endometriosis could induce higher percentage of CD163+ macrophages and upregulate mRNA levels of CD86, CD163, and IL-12." (PMID 30276219, 2018). "In addition, the mRNA levels of CD86 and CD163 as well as the cytokine IL-12 were significantly higher in macrophages treated with serum from endometriosis patients than in those treated with serum from normal controls." (PMID 30276219, 2018). "In addition, the expression levels of CD163 mRNA and CD86 mRNA as well as cytokine IL-10 mRNA were not significantly different between the two groups, whereas the expression of IL-12 mRNA in the peritoneal macrophages of endometriosis patients was decreased, as compared with that in control samples." (PMID 30276219, 2018).